ALDOB (aldolase, fructose-bisphosphate B)
Diseases named in the same sentence as ALDOB in open-access papers (continued):
Sharing a sentence is not in itself a finding about the gene and the disease.
tumor (continued). "Recently, ALDOB has been reported to be a tumor growth inhibitor." (PMID 40236649, 2025). "According to these findings, ALDOB might contribute to tumor development and progression in individuals with ccRCC." (PMID 40852386, 2025). "The HR value of 2.742 indicates that higher methylation levels of ALDOB might be involved in tumor progression." (PMID 39348357, 2024). "Furthermore, analysis of clinical data also indicated that ALDOB levels markedly correlated with the tumor invasion depth (P = 0.015), LNM (P = 0.003), and TNM stage (P = 0.008)." (PMID 37576390, 2023). "ALDOB mRNA was found to be elevated in tumor tissue (P = 0.011)." (PMID 37816733, 2023). "As we observed a correlation between higher tumor ALDOB expression and elevated circulating CEA levels in patients, we sought to determine if increased ALDOB expression could promote CEA expression." (PMID 37816733, 2023). "It was observed that ALDOB expression was significantly elevated in tumor tissue (P = 0.004)." (PMID 37816733, 2023). "Aberrant loss of ALDOB and upregulation of glycolysis in HCC tumor cells." (PMID 37881434, 2023). "Additionally, deeper invasion (T3-4) tumor tissues showed reduced ALDOB levels than those with T1-2 (P < 0.05)." (PMID 37576390, 2023). "In cancers, ALDOB's role is contentious as it can act as an anti-tumor or oncogenic enzyme." (PMID 37576390, 2023). "Alternatively, the gene ALDOB is ~5-fold downregulated in analyzed tumor samples." (PMID 35096203, 2022). "ALDOB protein expression was similarly decreased in IHC findings in HCC than that in adjacent normal tissues (P<0.05) and was significantly associated with tumor size (P<0.001), high tumor-node-metastasis stage (P=0.022), and elevated SUVmax (P=0.009)." (PMID 36644641, 2022). "Previous evidence has indicated that ALDOB has a dual function in tumor progression." (PMID 33282950, 2020). "Furthermore, ALDOB downregulation in ccRCC leads to accumulation of fructose-1,6-bisphosphate and disrupts redox homeostasis, whereas ALDOB upregulation restores metabolic balance and inhibits tumor progression." (PMID 40520908, 2025). "However, ALDOB expression did not exhibit any significant association with tumor size and location, or patients' gender (P > 0.05)." (PMID 37576390, 2023). "By performing a differential analysis between the two tumor cell compartments, we found that numerous genes associated with antigen presentation (e.g., HLA-DRA, CD74) were intensively upregulated in APHC, while a variety of metabolic enzymes (e.g., CYP3A5, ALDOB) were highly expressed in ANHC." (PMID 37336873, 2023). "Furthermore, tumours without KRAS gene mutation show overexpression of ALDOB and CPS1 and downregulation of PGAM4 genes, which are involved in metabolic pathways such as biosynthesis of amino acids, gluconeogenesis, glycolysis and carbon metabolism." (PMID 31949199, 2020). "Additionally, the dysregulation of ALDOB and IGF2 caused by hypermethylation and abnormal miRNA regulation through the mediation of miR-21 and miR-29a, respectively, might facilitate tumor metastasis." (PMID 30344796, 2018). "However, since it is difficult to eliminate MG, whether ALDOB inhibits tumor migration mainly through MG is still unclear." (PMID 26376879, 2015). "Fructose metabolism, particularly through key enzymes such as ketohexokinase (KHK) and aldolase B (ALDOB), along with the fructose transporter GLUT5, supports tumor growth, metastasis, and therapeutic resistance." (PMID 40520908, 2025). "By utilizing the marker genes of HCC tumor cells, such as albumin (ALB) and aldolase 2 (ALDOB), we distinguished the malignancy clusters from immune cells and stromal cells." (PMID 39095854, 2024). "The downregulation of ALDOB by STAT3 and GATA2 promotes enhanced glycolytic flux, which is essential for meeting the increased energy demands of rapidly dividing tumor cells." (PMID 39348357, 2024).
tumor (continued). "This analysis was performed using specific marker genes: GPX3 and ALDOB for proximal tubular cells and VIM, KRT18, NDUFA4L2, and NNMT for tumor cells." (PMID 37533434, 2023). "Consistent with the observations in mouse tumors, epithelial KPC tumor organoids exhibited higher GLUT5, KHK, ALDOB protein levels, and higher activity of KHK compared to the normal KP organoids." (PMID 37559908, 2023). "This investigation provides evidence that ALDOB levels were decreased in GC tissues than in normal adjacent tissues, and was decreased more in LNM patients, terminal stage of TNM, and enhanced tumor size." (PMID 37576390, 2023). "Similar with results from TCGA-KIRC and GSE126964, the expression of ALDOB, ESRRG, and EFHD1 were much lower in tumor cells than that in other intrinsic renal cells." (PMID 34660292, 2021). "Increased ALDOB and ALDOC expression can lead to Wnt-signaling pathway activation in tumor cells, which contributes to disease progression." (PMID 30967137, 2019). "We examined the expression of ALDOB in 25 cases of PVTT, matched primary tumors and non-tumor tissues." (PMID 26376879, 2015). "Stable expression of ALDOB in HCC cell lines reduced cell migration in vitro and inhibited lung metastasis, intrahepatic metastasis, and reduced circulating tumor cells in vivo." (PMID 26376879, 2015). "Moreover, ALDOB synergizes with SLC16A4 to drive both the glycolytic and fructose metabolic pathways, further enhancing tumor cell survival and proliferation." (PMID 40520908, 2025). "PTGR1, C1orf115, CRYL1, ALDOB, and SULT1B1 may be tumor suppressor genes involved in GC progression." (PMID 38737262, 2024). "Negative ALDOB expression in tumor tissue was correlated with tumor size (P<0.001), high tumor-node-metastasis (TNM) stage (P=0.022), and elevated SUVmax (P=0.009)." (PMID 36644641, 2022). "ALDOB overexpression in HUH7 and 7721 cells was used to analyze its role in tumor metabolism." (PMID 36644641, 2022). "Patients with a high TNM stage had negative ALDOB expression in tumor tissues, and all ALDOB-positive patients were stage I." (PMID 36644641, 2022). "Here, reduced expression of ALDH8A1, ALDOB and ARG1 were also shown in tumor tissues." (PMID 35036167, 2021). "Downregulated ALDOB is correlated with the absence of encapsulation, tumor size and early recurrence in HCC." (PMID 35036167, 2021). "Indeed, we showed that down-regulated Aldob attenuated PP2A interaction and dephosphorylation of Akt, which was consistent with the inverse relationship between Aldob and p-Akt expression in tumor tissues of human HCC and ALDOB KO mice." (PMID 33275593, 2020). "In addition, it has been proposed that the dysregulations of HSPB1, ALDOB, and RPL30 are sufficient to trigger tumor progression." (PMID 30344796, 2018). "In addition, it has been proposed that the dysregulation of DNA methylation of RPL30, ALDOB, IGF2, and TIMP1 is sufficient to trigger tumor progression." (PMID 30344796, 2018). "ALDOB downregulation correlated with female gender (P = 0.016), tumor size >5 cm (P = 0.006), absence of encapsulation (P = 0.002) and early recurrence (P = 0.002)." (PMID 26376879, 2015). "This analysis revealed that ALDOB downregulation was significantly correlated with female gender (P = 0.016), tumor size >5 cm (P = 0.006), absence of encapsulation (P = 0.002) and early recurrence (P = 0.002)." (PMID 26376879, 2015). "However, when patient subgroups were stratified based on the ratio of ALDOB levels in tumor and nontumor tissues, those with high tumor ALDOB expression (T > N) showed significantly increased ECAR (P = 0.034) and a borderline increase in OCR (P = 0.053)." (PMID 37816733, 2023). "Conversely, hepatic periportal markers (e.g., ALDOB, HAL, ASS1) and a subset of CYP-related proteins (e.g., CYP2A6, CYP2A7, CYP2B6) were either absent or downregulated in the tumor region." (PMID 39567475, 2024).
tumor (continued). "We finally obtained a list of only five genes (AGXT; ALDOB; CYP2E1; IGFBP3; TOP2A) that were differentially expressed in tumor and nontumor tissues across studies, and were significantly correlated to HCC prognosis." (PMID 31771612, 2019). "ALDOB downregulation in HCC was significantly correlated with aggressive characteristics including absence of encapsulation, increased tumor size (>5 cm) and early recurrence." (PMID 26376879, 2015).
cancer (30 papers, 2015 to 2025). A tumor composed of atypical neoplastic, often pleomorphic cells that invade other tissues. "The investigation demonstrates that when hyperactive AKT is targeted by direct inhibition of AKT activity or by reactivating PP2A phosphatase, it may act as a potential treatment strategy for ALDOB-deficient human cancers." (PMID 37576390, 2023). "ALDOB is important for the proliferation and invasion of cancer cells, and its overexpression is used as a prognosis biomarker for different adenocarcinomas in humans." (PMID 35746618, 2022). "Moreover, our supplementary investigations revealed that ALDOB functions as a crucial prognostic indicator across multiple cancer varieties." (PMID 40852386, 2025). "Using the TCGA dataset, ALDOB mRNA expression levels in pan-cancer samples were initially analyzed." (PMID 40852386, 2025). "Several cancers, including ccRCC, have markedly lower levels of ALDOB mRNA than normal tissues." (PMID 40852386, 2025). "The role of ALDOB in cancer is still controversial and more exploration is mandatory." (PMID 37371512, 2023). "Alterations in ALDOB activity also impact cancer aggressiveness." (PMID 34436420, 2021). "Previous studies have shown that the absence of ALDOB leads to the loss of Akt inhibition, promotes the development of cancer and indicates a poor prognosis." (PMID 34722497, 2021). "ALDOB may serve a controversial function in various cancer types, according to previous studies." (PMID 40852386, 2025). "The TCGA dataset was utilized to determine whether ALDOB’s low expression is widespread in cancer." (PMID 40852386, 2025). "Moreover, the anti-cancer effects of ALDOB in other cancer types have been confirmed." (PMID 40520908, 2025). "Considering ALDOB negatively modulates AKT activation in HCC 19 and AKT is crucial for cancer cell's ability to proliferate and migrate 21, 22, it was hypothesized whether the AKT signaling pathway is implicated in ALDOB modulation of GC cell ability to proliferate and migrate." (PMID 37576390, 2023). "Thus, ALDOB has controversial roles which depend on the type of cancer." (PMID 37576390, 2023). "Insights into fructose's contribution to cancer cell metabolism emphasize its role in promoting cell survival, particularly via pathways that involve ketohexokinase (KHK) and aldolase B (ALDOB)." (PMID 40520908, 2025). "ALDOB is transcriptionally induced by GATA6 and promotes fructose metabolism, which provides metastasizing cancer cells with the energy and materials necessary for increased growth." (PMID 38200154, 2024). "Of these, ALDOB, WNT11, MSLN, RAC3, and IL1RN have known roles in CRC, FBLX16 has known roles in other cancers, and SLC38A11 and WBSCR27 are relatively uncharacterized." (PMID 38680862, 2024). "The genes with CNV amplifications exhibited a significantly higher expression in cancer tissues than in normal controls (e.g., HK3 and ENO2), while the genes with CNV deletions exhibited significantly lower expression (e.g., ALDOB and PSAT1)." (PMID 33564363, 2021). "Additionally, ALDOB exhibits altered expression in HCC, where its dysregulated activity is similarly tied to the progression and metastasis of cancer 186-188." (PMID 40520908, 2025). "ALDOB and ALOX12 have been reported to be involved in fructose-induced cancer metastasis." (PMID 38200154, 2024). "Notably, key players in glycolysis such as ALDOB and KDELR3 genes are increased in LYZ+ cancer cells." (PMID 38659853, 2024). "Furthermore, little is known about the roles of ALDOB, CRYL1, and C1orf115 in human cancer, especially GC, so future studies on these genes are needed." (PMID 38737262, 2024). "To assess the clinical significance of ALDOB in HCC, we queried the RNA sequencing data from The Cancer Genome Atlas (TCGA) database using GEPIA and found that ALDOB mRNA levels were downregulated in HCC (normal versus cancer)." (PMID 36644641, 2022).
metabolic disorders (3 papers, 2020 to 2025). "The KHK-A knock-out aggravated the metabolic profile in AldoB knock-out mice, suggesting that KHK-A plays a protective role in the fructose-mediated metabolic disorders." (PMID 33116123, 2020). "In addition to these genes, variants were found in seven genes (ALDOB, MASP1, KIAA1109, TRAPPC4, SMARCAL1, HERC1, RRAS2) that were previously not reported in MPS but associated with other metabolic disorders." (PMID 37091798, 2023).
infection (1 paper, 2009). The state of being infected such as from the introduction of a foreign agent such as serum, vaccine, antigenic substance or organism. "The increased gluconeogenesis during LCMV infection resembled that seen during starvation or cachexia, however the infection also up-regulated mRNA encoding glycolytic enzymes (PGK1, GCK, GAPDH and ALDOB) that are usually down-regulated during a fast." (PMID 19216742, 2009).
ALDOB also shares sentences with these, for which no sentence is quoted: colorectal adenocarcinoma (2 papers); genetic diseases (2); liver failure (2); -intestinal inflammation (1); adenocarcinoma (1); amyloidosis (1); atherosclerosis (1); Bardet-Biedl syndrome (1); bladder tumor (1); celiac disease (1); cholangiocarcinoma (1); esophageal carcinoma (1); Fanconi syndrome (1); hemorrhoid (1); Hepatitis (1); hereditary cancer (1); hyperlipidemia (1); hypophosphatemia (1); Insulin resistance (1); lactic acidosis (1); lipid metabolism disorders (1); liver (1); liver cirrhosis (1); liver disease (1); liver neoplasm (1); lysosomal storage disorders (1); malaria (1); McArdle disease (1); metastatic cancer (1); non-alcoholic fatty liver disease (1).
A further 6 diseases each share a sentence with ALDOB in 1 paper.